GREM1 (gremlin 1, DAN family BMP antagonist)
Diseases named in the same sentence as GREM1 in open-access papers (continued):
Sharing a sentence is not in itself a finding about the gene and the disease.
breast carcinoma (continued). "Human cancers such as gastric, colorectal, glioblastoma, and breast cancer are characterized by GREMLIN1 (GREM1) overexpression, leading to inhibition of BMP signaling, facilitating the maintenance of pluripotency in CSCs, thus promoting tumorigenesis." (PMID 40277903, 2025). "GREM1 disrupts BMP/SMAD signaling in breast cancer cells, promoting their mesenchymal phenotype, stemness, and invasion." (PMID 40940956, 2025). "GREM1 abrogated bone morphogenetic protein (BMP)/SMAD signaling in breast cancer cells, and also promoted the fibrogenic activation of CAFs." (PMID 39544302, 2024). "High expression of GREM1 promotes the growth and proliferation of tumor cells in breast cancer and glioma, but inhibits the development of tumors in osteosarcoma and pancreatic ductal adenocarcinoma." (PMID 38970064, 2024). "Transforming growth factorβ(TGFβ) secreted by breast cancer cells, stimulated GREM1 expression in CAFs." (PMID 39544302, 2024). "TGFβ secreted by breast cancer cells can stimulate bone morphogenetic protein (BMP) antagonist GREMLIN1 (GREM1) in CAFs." (PMID 36624542, 2023). "Docosahexaenoic acid (DHA) can prevent GREM1-induced EMT in breast cancer cells by targeting ERK signalling." (PMID 37333824, 2023). "High levels of GREM1 are also associated with poorer patient prognosis in, for example, colorectal and breast cancer, suggesting an oncogenic function for GREM1 in cancer." (PMID 37615860, 2023). "GREM1-mediated EGFR activation was suggested to enhance the promoter activity of estrogen-related receptor alpha (ERRα), which is predicted to bind to the GREM1 promoter to increase GREM1 expression and drive breast cancer cell proliferation." (PMID 37615860, 2023). "TGFβ-induced Grem1 expression in breast cancer CAFs promoted a mesenchymal phenotype, stemness and invasion of tumor cells." (PMID 37615860, 2023). "For example, the knockdown of GREM-1 led to a decrease in the proliferation potential of breast cancer cells." (PMID 35203511, 2022). "In one study, the expression analysis of clinical breast cancer datasets revealed that the high expression of GREM1 in breast cancer stroma was correlated with a poor prognosis regardless of the molecular subtype." (PMID 36430403, 2022). "In patients with breast cancer or CRC, high expression of GREM1 is usually associated with poor prognosis." (PMID 35883579, 2022). "TGF-β and inflammatory cytokines secreted by breast cancer cells induced CAFs to express gremlin 1 (GREM1), abrogating BMP/SMAD signaling and promoting stemness and invasion of cancer cells." (PMID 36185262, 2022). "Transforming growth factor β (TGFβ)—secreted by breast cancer cells—and inflammatory cytokines stimulated GREM1 expression in CAFs." (PMID 36430403, 2022). "On the contrary, overexpression of GREM-1 induced growth, migration, and invasion of breast cancer cells." (PMID 35203511, 2022). "In breast cancer, GREM1 was shown to be an oncogenic protein by promoting tumor cell proliferation, migration, and invasion, which is associated with worsening of survival." (PMID 34283070, 2021). "In support of this postulation, the breast cancer cell lines overexpressing GREM1 had significantly higher transcriptional activity of ERRα than the respective control cell lines." (PMID 32572171, 2020). "As an initial approach to assess a role of GREM1 in breast cancer development, we first examined the level of GREM1 in some transformed or cancerous human breast cell lines as compared to non-cancerous human breast epithelial cells (MCF-10A)." (PMID 32572171, 2020). "To confirm the role of GREM1 in the growth and migration of breast cancer cells, we silenced endogenous GREM1 expression in two breast cancer cell lines (MDA-MB-231 and MTV/TM-011) using a lentiviral transduction system." (PMID 33287358, 2020). "Like ERRα activity, the mRNA levels of ERRα target genes, KLK3, ENO1 or TAPBPL, were also significantly elevated in GREM1-overexpressing breast cancer cells." (PMID 32572171, 2020).
breast carcinoma (continued). "Taken together, DHA has an inhibitory effect on EMT in breast cancer cells through suppressing GREM1 expression and/or GREM-induced ERK activation." (PMID 32141512, 2020). "The role of GREM1 in breast cancer progression was assessed by measuring growth, migration, and invasion of breast cancer cells." (PMID 33287358, 2020). "Our study suggests that GREM1 can promote lung metastasis of breast cancer cells through the STAT3-MMP13 pathway." (PMID 33287358, 2020). "There is evidence supporting that the aberrant overexpression of epithelial GREM1 is involved in colon cancer development and progression, but the role of GREM1 in pathogenesis of breast cancer remains elusive." (PMID 32572171, 2020). "The role of GREM1 in breast cancer progression was assessed by measuring cell viability, colony formation, 3D tumour spheroid formation/invasion and xenograft tumour formation." (PMID 32572171, 2020). "GREM1 activated ERK signaling, which played an important role in GREM1-induced EMT in human breast cancer cells." (PMID 32141512, 2020). "GREM1 increased expression levels of mesenchymal cell-related proteins and ultimately enhanced the migration of breast cancer cells." (PMID 32141512, 2020). "Immunofluorescence staining of human breast cancer tissue microarrays showed that GREM1 was overexpressed in ER-positive and ER-negative breast cancer tissues compared to normal breast tissues." (PMID 32572171, 2020). "BALB/c athymic nude mice received the subcutaneous injection of control, GREM1-silenced or GREM1-overexpressing SKBR3 breast cancer cells." (PMID 32572171, 2020). "The result showed that GREM1 is the most consistently highly expressed gene across breast carcinomas." (PMID 32141512, 2020). "Our present study demonstrates that GREM1 can increase tumor promotion and lung metastasis of breast cancer cells." (PMID 33287358, 2020). "GREM1 can activate Slug or Smad to induce EMT in human breast cancer cells or tubular epithelial cells, respectively." (PMID 33287358, 2020). "To determine the clinical relevance of GREM1 expression to breast cancer progression, we used the Oncomine database." (PMID 32572171, 2020). "This suggestive feed forward loop between CAFs and malignant cells was further reinforced by results showing that GREM1 expression is restricted to tumor stroma in breast cancer patients." (PMID 32733895, 2020). "To confirm the effect of GREM1 on migratory ability of breast cancer cells, we used a wound healing assay." (PMID 33287358, 2020). "GREM1 can enhance the activity of estrogen-related receptor α and lead to the progression of breast cancer." (PMID 33287358, 2020). "The level of GREM1 expression in human breast cancer tissues was determined by Oncomine database mining." (PMID 32141512, 2020). "GREM1 expression was elevated in breast cancer cells and tissues obtained from breast cancer patients." (PMID 32572171, 2020). "GREM1 knockdown inhibited the proliferation of breast cancer cells and xenograft mammary tumour growth, while its overexpression enhanced their viability, growth and invasiveness." (PMID 32572171, 2020). "The effective concentration (10 μM) of XCT790 significantly reduced both expression of GREM1 and viability of these breast cancer cells." (PMID 32572171, 2020). "In the meta-analysis, GREM1 expression was significantly higher in breast carcinoma tissues than in corresponding normal tissues, with a median rank of 27 and a p-value of 2.35 × 10−4." (PMID 33287358, 2020). "Taken together, these findings clearly demonstrate that GREM1 is essential for the growth and progression of breast cancer cells." (PMID 32572171, 2020). "Taken together, these results suggest that DHA can inhibit GREM1-induced EMT by suppressing ERK activation in human breast cancer cells." (PMID 32141512, 2020). "Overall, these results indicate that GREM1 plays an important role in promoting breast cancer cell growth, migration, and invasion." (PMID 33287358, 2020).
breast carcinoma (continued). "GREM1 knockdown significantly suppressed the viability and the colony formation of multiple ER-negative human breast cancer cell lines as well as H-ras-transformed human mammary epithelial cells." (PMID 32572171, 2020). "We further investigated the level of GREM1 expression in human breast carcinoma tissues using Oncomine database." (PMID 32141512, 2020). "The protein expression of GREM1 was found to be markedly elevated in breast cancer cell lines, particularly ER-negative ones, including MDA-MB-468, MDA-MB-453 and SKRB3 cells." (PMID 32572171, 2020). "An orthotopic breast cancer mouse model was used to investigate the role of GREM1 in lung metastasis of breast cancer cells." (PMID 33287358, 2020). "In the present study, we demonstrated that GREM1 physically interacted with EGFR in breast cancer cells and thereby activates EGFR signalling." (PMID 32572171, 2020). "GREM1 knockdown suppressed the proliferation of breast cancer cells, while its overexpression increased their growth, migration, and invasion." (PMID 33287358, 2020). "In this study, we found a novel function of GREM1 as an oncogenic protein in breast cancer growth and progression." (PMID 32572171, 2020). "CAFs-derived GREM1 can increase mesenchymal phenotype, stemness, and invasion of breast cancer cells." (PMID 33287358, 2020). "We provide mechanistic insights into GREM1’s key role in facilitating breast cancer progression using in vitro and in vivo studies." (PMID 31533776, 2019). "To further characterize the role of Grem1 in breast cancer, we stably expressed Grem1 in the breast cancer cell lines M2 and MDA-MB-231 with a lentiviral vector." (PMID 31533776, 2019). "The results presented here support the idea that Grem1 is a clinical predictor of a poor prognosis in breast cancer." (PMID 31533776, 2019). "Grem1 abrogated bone morphogenetic protein (BMP)/SMAD signaling in breast cancer cells and promoted their mesenchymal phenotype, stemness, and invasion." (PMID 31533776, 2019). "The effects of Grem1 on the properties of breast cancer cells were assessed by measuring the mesenchymal/stem cell marker expression and functional cell-based assays for stemness and invasion." (PMID 31533776, 2019). "Grem1 has a direct effect on cancer cell invasion and stemness, evidenced by the fact that it promoted a slightly more mesenchymal/stemness phenotype in breast cancer cells." (PMID 31533776, 2019). "Grem1 is highly expressed by CAFs at the invasion front; its expression can be promoted by factors, such as TGFβ released by breast cancer cells and inflammatory cytokines." (PMID 31533776, 2019). "In this way, Grem1 promotes the formation of a microenvironment conducive to breast cancer cell invasion." (PMID 31533776, 2019). "Mechanistically, Grem1 produced by CAFs promoted fibroblast activation in an autocrine manner and stimulated breast cancer cell stemness and invasion in a paracrine manner." (PMID 31533776, 2019). "The role of Grem1 in CAF-induced breast cancer cell intravasation and extravasation was studied by utilizing xenograft zebrafish breast cancer (co-) injection models." (PMID 31533776, 2019). "To explore the role of Grem1 in fibroblast activation, we first compared GREM1 mRNA expression levels in foreskin fibroblasts, 19TT breast cancer CAFs, and HM, W18, and W21 human mesenchymal stem cells (MSCs)." (PMID 31533776, 2019). "Using publicly available databases, we found that GREM1 is also expressed on mRNA level by various human breast cancer cell lines and that GREM1 is significantly upregulated in primary tumor biopsies of breast cancer patients compared to normal tissue samples." (PMID 31694641, 2019). "We determined which cells express GREM1 RNA using in situ hybridization (ISH) on a breast cancer tissue microarray." (PMID 31533776, 2019). "In this study, we mined the prognostic role of BMP antagonists GREMLIN 1 (GREM1) in primary breast cancer tissues using in-house and publicly available datasets." (PMID 31533776, 2019).
breast carcinoma (continued). "3D co-culture of breast cancer cells with CAFs in collagen demonstrated that Grem1 is critical for invasion." (PMID 31533776, 2019). "We found that 10% (6 out of 60) breast cancer cell lines expressed elevated GREM1 mRNA levels compared to the average of > 1000 different cell lines." (PMID 31694641, 2019). "GREM1 overexpression (OE) in W21 mesenchymal stem cells (MSCs) promotes breast cancer cells intravasation in zebrafish embryo perivitelline space coinjection model." (PMID 31533776, 2019). "Our results identified Grem1 as a driving force of breast cancer progression by affecting the behavior of both cancer cells and neighboring CAFs." (PMID 31533776, 2019). "Transforming growth factor β (TGFβ) secreted by breast cancer cells, and also inflammatory cytokines, stimulated GREM1 expression in CAFs." (PMID 31533776, 2019). "Our results demonstrated that Grem1 is a pivotal factor in the reciprocal interplay between breast cancer cells and CAFs, which promotes cancer cell invasion." (PMID 31533776, 2019). "In summary, these data indicate that in contrast to other BMP-antagonists, high GREM1 expression is particularly relevant for aggressive tumor development in breast cancer patients." (PMID 31694641, 2019). "The reciprocal interaction between breast cancer cells and CAFs is mediated in part by GREM1." (PMID 40069570, 2025). "Furthermore, GREM1 overexpression increased the growth, migration, and invasion of breast cancer cells, and cells with GREM1 silencing showed reduced tumor growth rates and lung metastasis, which highlighted the importance of GREM1 to metastasis." (PMID 40849639, 2025). "Breast cancer patients with high expression of GREM1 have a poor prognosis." (PMID 38970064, 2024). "These processes enhance the invasive ability of cancer cells, so the treatment of GREM1 targets may improve the prognosis of breast cancer patients with high GREM1 expression." (PMID 39544302, 2024). "In addition, Grem1 abolished bone morphogenetic protein (BMP)/SMAD signaling in breast cancer cells and promoted their mesenchymal phenotype, stemness, and invasion." (PMID 36430403, 2022). "Moreover, knock-down of GREM1 was found to result in decreased proliferation of breast cancer cells." (PMID 34283070, 2021). "GREM1 can also promote lung metastasis in breast cancer cells through the STAT3-MMP13 pathway." (PMID 34452576, 2021). "Recently, GREM1 was reported to activate STAT3 signaling in breast cancer cells." (PMID 33967807, 2021). "In the present study, we examined a role of GREM1 as an EMT inducer in human breast cancer cells." (PMID 32141512, 2020). "The objective of this study was to examine the oncogenic role of GREM1 in breast cancer." (PMID 33287358, 2020). "GREM1 overexpression enhanced the cell proliferation and mobility of these breast cancer cells." (PMID 33287358, 2020). "Next, we examined whether GREM1 induces mitogen activated protein kinases (MAPKs) or protein kinase Akt in human breast cancer cells." (PMID 32141512, 2020). "The function of GREM1 in lung metastasis of breast cancer cells was also determined." (PMID 33287358, 2020). "Herein, we report the oncogenic role of GREM1 in breast cancer growth and progression." (PMID 32572171, 2020). "Next, we investigated the role of GREM1 in the growth of breast cancer cells." (PMID 32572171, 2020). "In addition, several genes associated with the extracellular matrix, metalloendopeptidase activity, or angiogenesis were coexpressed with GREM1 in human breast carcinomas." (PMID 33287358, 2020). "However, molecular mechanisms by which GREM1 induces breast cancer metastasis remain largely unresolved." (PMID 33287358, 2020). "By adding a set of genes through the extracellular matrix, metalloendopeptidase activity, or angiogenesis filter, the level of GREM1 expression was compared with levels of multiple genes corresponding to each filter in four independent breast carcinoma analyses." (PMID 33287358, 2020).
breast carcinoma (continued). "Therefore, development of chemical or biological agents to selectively targeting the aberrantly overactivated GREM1–ERRα axis merits further investigation in the context of their potential application for the treatment of breast cancer." (PMID 32572171, 2020). "We then determined whether GREM1 expression, regulated by ERRα, could stimulate receptors involved in breast cancer cell growth." (PMID 32572171, 2020). "However, it has rarely been reported that increased specific kinase activity by GREM1 induces EMT of breast cancer cells." (PMID 32141512, 2020). "Results showed that GREM1 was the most consistently highly expressed gene across multiple independent breast carcinoma analyses, indicating that GREM1 might be a potent prognostic biomarker in breast cancer patients." (PMID 33287358, 2020). "The invasive capability of the spheroids derived from GREM1-silenced SKBR3 breast cancer cells co-cultured with CCD-1068sk breast fibroblasts was significantly reduced compared to that of the spheroids formed by co-culture of CCD-1068sk and control breast cancer (SKBR3-shCtrl) cells." (PMID 32572171, 2020). "Our results showed that GREM1 is a new inducer of EMT in human breast cancer cells." (PMID 32141512, 2020). "In all breast cancer cases, elevated levels of GREM1 and SMAD6 correlated with poor prognosis." (PMID 31694641, 2019). "Moreover, Grem1 production by CAFs strongly promoted the fibrogenic activation of CAFs and promoted breast cancer cell intravasation and extravasation in co-injection xenograft zebrafish models." (PMID 31533776, 2019). "Targeting Grem1 could be beneficial in the treatment of breast cancer patients with high Grem1 expression." (PMID 31533776, 2019). "Taken together, the elevated GREM1 mRNA found in breast cancer biopsies could either come from the cancer cells themselves, or from cells infiltrating the tumor." (PMID 31694641, 2019). "Notably, the mRNA levels of the mesenchymal markers SLUG, SNAI1, VIM, and NCAD were increased by ectopic GREM1 expression or exogenous rhGrem1 treatment, suggesting that Grem1 induces a slightly more mesenchymal phenotype in these breast cancer cells." (PMID 31533776, 2019). "qRT-PCR revealed that GREM1 OE or rhGrem1 increased the expression of transcriptional regulators YAP, TAZ, SOX2, and OCT4, which have been implicated in maintaining breast cancer stemness." (PMID 31533776, 2019). "a GREM1 mRNA expression in epithelium and stroma compartments in breast cancer dataset GSE14548." (PMID 31533776, 2019). "Interestingly, all the 13 breast cancer cell lines that expressed GREM1 co-expressed at least one of the three BMPs, with BMP4 being most commonly co-expressed." (PMID 31694641, 2019). "We then asked if any of the extracellular antagonists besides GREM1, or inhibitory SMADs, could predict prognosis of breast cancer patients." (PMID 31694641, 2019). "Next, we examined the role of fibroblast-expressed Grem1 in breast cancer cell invasion in vivo." (PMID 31533776, 2019). "Combined, these data demonstrate that breast cancer cells may co-express BMPs and GREM1, and that co-expression of BMP and GREM1 in breast cancer biopsies does not reduce GREM1’s value as a predictor of poor outcome." (PMID 31694641, 2019). "Targeting GREM1 could benefit the treatment of breast cancer patients with high Grem1 expression." (PMID 37692495, 2024). "By adding a set of genes through the TGF-β signal pathway filter, the expression level of GREM1 could be compared with the levels of multiple genes corresponding to the TGF-β signal transduction pathway through four independent breast carcinoma versus normal analyses." (PMID 32141512, 2020). "Importantly, GREM1 is overexpressed in several types of cancers including breast cancer." (PMID 33287358, 2020). "However, little is known about how GREM1 promotes breast cancer cell metastasis." (PMID 33287358, 2020).